MIF (macrophage migration inhibitory factor)
Diseases named in the same sentence as MIF in open-access papers (continued):
Sharing a sentence is not in itself a finding about the gene and the disease.
tumor (continued). "MIF is produced and secreted by both monocytes/macrophages and tumour cells and has pro-tumourigenic activities in vitro." (PMID 19602265, 2009). "In turn, induced tumour cell-derived MIF was critical for invasiveness of tumour cells and MMP9 secretion by macrophages." (PMID 19602265, 2009). "MIF has been demonstrated to directly and indirectly act as a chemoattractant for leukocytes, fibroblasts, and tumour cells." (PMID 19602265, 2009). "When coculturing MCF-7 cells with human macrophages, MIF was identified as a prominent target in tumour cells that was upregulated upon inflammatory cytokine production by cocultured macrophages." (PMID 19602265, 2009). "Intra-tumoural MIF levels correlated with proinflammatory macrophage cytokines, suggesting that MIF regulates and is regulated by tumour-stroma interactions, particularly in cancers with minimal nodal spread." (PMID 19602265, 2009). "MIF is overexpressed in various tumours and has been suggested as a molecular link between chronic inflammation and cancer." (PMID 19602265, 2009). "TNFα-triggered tumour cell-derived MIF led to increased macrophage metalloproteinase production rates and facilitated tumour cell invasion." (PMID 19602265, 2009). "Our study adds another puzzle stone to the role of MIF in tumor growth and progression by showing the importance of MIF for overcoming contact inhibition." (PMID 20038293, 2009). "Macrophage migration inhibitory factor is a pro-inflammatory cytokine, which is able to promote tumour cell proliferation, migration and metastasis and tumour angiogenesis." (PMID 19550422, 2009). "In tumours, the MØs can promote tumour cell angiogenesis, invasion and survival by up-regulating genes such as GLUT-1, VEGF, CXCR4 and MIF and high levels of these tumour-associated macrophages (TAMs) can predict poor patient survival." (PMID 18507854, 2008). "Several studies also indicate that MIF expression closely correlates with tumor aggressiveness and metastatic potential, suggesting as important contribution to cancer malignancy by MIF." (PMID 18493321, 2008). "Macrophage migration inhibitory factor (MIF) is a ubiquitously expressed pro-inflammatory mediator that has also been implicated in the process of oncogenic transformation and tumor progression." (PMID 17640378, 2007). "Indications of MIF's key role in tumor progression derive from studies where treatments with either anti-MIF immunoglobulin therapy and/or MIF antisense oligonucleotide confer anti-tumor activity." (PMID 16000172, 2005). "Moreover, resistant tumor cells enhanced macrophage tolerance to cisplatin via the MIF axis, an effect that was reversed by pharmacological MIF inhibition." (PMID 41724379, 2026). "Consistently, spatial transcriptome and mIHC analyses using adjacent sections show that TLS regions containing MIF+ tumor cells (SOX2+) are enriched with exhausted T cells (CD3+PD-1+TIM-3+) and exhausted B cells (CD20+CD21-CD27-PD-1+), indicating an impaired B-cell immune response." (PMID 41355948, 2026). "Subsequent analysis utilizing the CellPhoneDB-secreted ligand‒receptor database revealed that tumor cells with high PSMD1 expression predominantly employ ligands such as MIF, MDK, and SPP1 as signaling molecules to communicate with immune cells within the microenvironment." (PMID 41535254, 2026).
tumor (continued). "Analysis of both scRNA-seq and spatial transcriptomic data revealed that MIF is expressed across various cell types, with the highest levels observed in malignant cells, particularly those identified as cholesterol biosynthesis-related tumor cells." (PMID 41355948, 2026). "In summary, these data suggested a hypothesis that cholesterol biosynthesis-related tumor cells with highly expressed MIF may correlate with disrupted GC reactions." (PMID 41355948, 2026). "Notably, MIF is a critical factor associated with malignant cell metastasis, as it impedes the cytotoxic activity of CD4+ and CD8+ T cells against local tumor cells." (PMID 41158758, 2026). "Our results showed that combined anti-MIF and anti–PD-1 significantly reduced tumor growth, improved survival, and promoted tumor regression, accompanied by enhanced TH1 cytokine levels, increased macrophage activation–related cytokines, and increased type 1 conventional dendritic cells." (PMID 41122966, 2025). "That led us to the more therapeutic question of whether acute ablation of epithelial MIF in established tumors might also reduce tumor growth and consequently, whether established tumors require epithelial MIF." (PMID 40835826, 2025). "Notably, MIF played a crucial role in tumor immune responses through interactions such as MIF - CD74/CD44." (PMID 40036264, 2025). "On the one hand, MIF can activate tumor cell proliferation contributing to tumor progression." (PMID 40761262, 2025). "Interestingly, the MIF secreted by tumor cells is a key factor to induce the transdifferentiation of myeloid cells into apCAFs through the JAK/STAT3 signaling pathway." (PMID 39891284, 2025). "Tumor cell-highCNs interacted with other cell types via MIF signaling pathway (P < .01)." (PMID 40052442, 2025). "Additionally, tumor-derived MIF inhibits T cell activation by inducing T cell death in an IFN-γ-dependent pathway." (PMID 41159021, 2025). "The results demonstrated that MIF was dysregulated in the majority of tumours." (PMID 40045162, 2025). "As a dynamic marker of tumor-immune interactions, MIF levels may also guide patient selection for immunotherapy or combination regimens." (PMID 41159021, 2025). "ICI administration in the morning may counteract the immunosuppressive functionality of MIF at its peak to reinvigorate the anti-tumor response and improve the clinical response of ICI." (PMID 40075580, 2025). "Our findings raise the possibility that tumor-derived MIF could engage CD74 on T cells, thereby disrupting their cytotoxic function and facilitating immune escape." (PMID 41155250, 2025). "While several prior studies have supported a role for MIF in tumor growth and aggressiveness, there are little data on the complex and dynamic roles of how MIF signaling directly impacts immune cell function, including recruitment, proliferation, and signaling." (PMID 40131169, 2025). "Preclinical studies show that MIF knockdown reduces tumor cell viability and apoptosis resistance." (PMID 41159021, 2025). "In our datasets, MIF was primarily expressed by tumor cells and less so by others cells in the TME." (PMID 39908652, 2025). "What remained unclear was whether this reduction in tumor progression resulted from protection during tumor initiation and/or from a functional switch of MIF in established tumors." (PMID 40835826, 2025). "We hypothesized that epithelial-derived MIF is essential for tumor maintenance and might serve as a possible cancer drug target." (PMID 40835826, 2025). "Additionally, it remains to be clarified which cellular sources of MIF - tumor epithelial cells, stromal cells, immune cells, or a combination - are critical for CRC maintenance." (PMID 40835826, 2025). "This indicates that, indeed, MIF secreted by tumor cells suppresses CAR T-cell activation." (PMID 39908652, 2025). "Additionally, we observed that myCAF_12 cells strongly interact with immune cells and regulate the tumor microenvironment via the MIF signaling pathway." (PMID 40303408, 2025).
tumor (continued). "Targeting MIF signaling for therapeutic purposes has emerged as a promising approach in oncology and virology, given its crucial role in tumor progression, viral persistence, and immunoregulation, although current data are mostly based on oncovirus-negative cancers." (PMID 41472252, 2025). "In the presence of MIF, myeloid cells exhibit pro-tumor effects." (PMID 39891284, 2025). "Moreover, the activation of MIF signaling exacerbates the immunosuppressive tumor microenvironment, limiting the activity of effector T cells." (PMID 40315269, 2025). "Moreover, HSP90-stabilized proteins, such as MIF, are secreted into the tumor microenvironment, where they further support tumor progression." (PMID 40835826, 2025). "Thus, nucleotide metabolism is not only a metabolic hallmark of CRC but acts as a central focal point that coordinates tumor-stromal-immune signaling (via MIF/PLA2/BAFF/TFRC) and spatially co-localizes with oncogenic pathways." (PMID 41450739, 2025). "Also, we unveiled that myeloid cells transdifferentiation was mediated by tumor cell-secreted MIF through the JAK/STAT3 signaling pathway." (PMID 39891284, 2025). "Complete inhibition of MIF signaling in immune cells, therefore, may have unexpected consequences in different tumor types given MIF's pleotropic effects on monocyte polarization, proliferation, antigen presentation, and T‐cell activation." (PMID 40131169, 2025). "Notably, the low genotypic human MIF expresser mice showed a similar reduction in tumor burden compared to the high genotypic human MIF expresser mice, mirroring results in the MIF-KO animals." (PMID 41122966, 2025). "Similarly, Shvefel and colleagues found Cd74 to be increased across several time points in the rejected clones and in response to MIF KO tumor clones in their scRNA‐seq analysis." (PMID 40131169, 2025). "Although predominantly characterized as a tumor promoter, MIF may exert context-dependent tumor-suppressive effects in certain context." (PMID 41159021, 2025). "Notably, MIF knockout models demonstrated a high reduction in Treg levels and increased anti-tumor immunity." (PMID 41159021, 2025). "Moreover, MIF contributes to survival and invasion of tumor cells as well as an immunosuppressive TME in bone marrow metastases." (PMID 39908652, 2025). "Additionally, tumor cell-highCNs potentially interacted with CD8 T cells via MIF and HLA related ligand-receptor pairs." (PMID 40052442, 2025). "In addition, we depicted the cell communication pathways in diverse immune and tumor cells including incoming and outgoing patterns, showing the importance of MIF signaling pathway." (PMID 40129974, 2025). "The RESISTIN and MIF pathways in MDSCs and epithelial cells were also enhanced; they may contribute to the chemotaxis of tumor-infiltrating immune cells." (PMID 39722065, 2025). "Incoming signals to PIAS1+ TAMs from tumor cells included elevated MIF–CD74_CD44 and MIF–CD74_CXCR4 interactions, which in this context may promote M1 polarization." (PMID 40941002, 2025). "Elevated MIF expression is often associated with decreased infiltration and impaired activity of CD8+ T cells, suggesting a negative regulatory role of MIF in TIL-mediated anti-tumor immunity." (PMID 40881277, 2025). "However, aberrant MIF expression within tumor cells has emerged as a key driver of tumorigenesis, contributing to multiple oncogenic pathways." (PMID 40835826, 2025). "Furthermore, AUC analysis at day 14 indicated a marked reduction in overall tumor burden in MIF-KO animals compared with WT (P = 0.0002)." (PMID 41122966, 2025). "Enhanced expression of MIF in tumor tissues suggested a potential oncogenic role of macrophages." (PMID 40936936, 2025). "Similarly, CTL-derived MIF directly suppressed the anti-tumor activity of primed cytotoxic T lymphocytes (CTLs)." (PMID 41159021, 2025). "In line, total tumor areas were reduced in MIF-depleted mice." (PMID 40835826, 2025).
tumor (continued). "If MIF is partially retained in tumors, it might affect surrounding tumor cells including the tumor microenvironment through paracrine actions." (PMID 40835826, 2025). "Collectively, these results demonstrate that loss or inhibition of MIF in solid tumors effectively reprograms intra-tumoral TAMs from an immunosuppressive, pro-angiogenic, tumor-promoting phenotype to an immunostimulatory, non-angiogenic, anti-tumor phenotype." (PMID 41159021, 2025). "MIF is reportedly a key regulator of tumorigenesis, angiogenesis, and tumor metastasis." (PMID 40880391, 2025). "Furthermore, targeted inhibition of MIF not only suppresses glycolysis but also significantly reduces tumor growth and metastasis." (PMID 40342932, 2025). "Moreover, anti-MIF neutralizing antibodies, MIF-directed RNA silencing, or small molecule MIF inhibitors have been tested in vitro and in preclinical tumor models with notable responses, but studies into the mechanisms of activity remain limited." (PMID 41122966, 2025). "Consequently, the therapeutic efficacy of immune checkpoint blockade, a strategy that aids the body’s immune system in attacking tumor cells, was enhanced by targeting MIF." (PMID 41159021, 2025). "The presence of MIF in the tumor microenvironment likely binds to CD74 on apCAFs." (PMID 39891284, 2025). "Tumour cells facilitate interactions with immune cells via MIF- and galectin-dependent pathways." (PMID 39901202, 2025). "Notably, we found that tumor cell‐derived GA‐dependent MIF mediates the formation of the immunosuppressive network through multi‐omics analysis and in vitro experiments." (PMID 39908165, 2025). "Functionally, MIF has been shown to promote tumor growth in preclinical models." (PMID 40835826, 2025). "Together, these findings confirm that the tumor-specific stabilization of MIF via HSP90 might be often an important driver of CRC progression and represents a selective vulnerability." (PMID 40835826, 2025). "Keep an eye on how important things in tumor-derived exosomes move about, including whether inflammatory substances like MIF and IL-6 can get across the vascular barrier and affect cardiomyocytes or cardiac immune cells, and so on." (PMID 40842994, 2025). "MIF facilitates the invasion and metastasis of tumor cells by binding to CXCR4." (PMID 40110199, 2025). "Moreover, our inducible, tissue-specific CRC models reveal that tumor cell-intrinsic MIF is critical for both tumor progression and maintenance, even in the presence of a fully functional stromal microenvironment." (PMID 40835826, 2025). "In addition, most MIF inhibitors lack tumor specificity and can impact normal physiological processes, leading to potential toxicity." (PMID 41159021, 2025). "However, where maturation of DCs is impeded by MIF, owing to the inability to effectively present tumor antigens, the activation of CTL cells is lowered, reducing anti-tumor immunity." (PMID 41159021, 2025). "However, the TH2 cytokine responses with dual anti–PD-1/anti-MIF therapy were mixed and likely reflect complex systemic signaling in tumor-bearing animals." (PMID 41122966, 2025). "CDK4/6i drives tumor cells to secrete MIF by activating the HIF-1α pathway." (PMID 41082324, 2025). "In terms of therapy, MIF raises the concentration of MDSCs in the bloodstream of individuals with diverse malignancies and employs multiple strategies to obstruct NK and T-cell activities, hence reducing anti-tumor immunity." (PMID 41159021, 2025).
tumor (continued). "Especially, the protein P115 on the GA is blocked, which in turn blocks the transporter of migration inhibitory factor (MIF), further reshaping the MIF‐mediated immunosuppressive network between tumor cells and various immune cells in the tumor microenvironment." (PMID 39908165, 2025). "In addition to TNF-α (Padj < 0.001), tumor tissue from the TNF-α High group secreted significantly higher levels of MIF and IL-10 (both Padj < 0.05)." (PMID 39923035, 2025). "Therefore, the study by Shvefel and colleagues is consistent with studies that have demonstrated MIF to be a driver of immune evasion, tumor aggressiveness, and poor clinical outcomes in animal models, as well as in retrospective patient clinical data." (PMID 40131169, 2025). "Furthermore, constant exposure to bevacizumab reduce tumor cell MIF expression and inevitably drives M1-to-M2 transition." (PMID 40058234, 2025). "Activation of CD74 via MIF is related to tumour growth and might mediate effects on proliferation in islet macrophages." (PMID 39508880, 2025). "MIF has a dual role in tumor development through modulating tumor growth and angiogenesis." (PMID 41159021, 2025). "Comparative analysis of intercellular communication characteristics between tumor and normal tissues found: significantly enhanced communication intensity of factors such as SPP1 and MIF in tumor tissues; more active communication networks involving SPP1 and lectins in normal tissues." (PMID 40958861, 2025). "Another research discovered that hypoxia-induced MIF causes deregulation of lipid metabolism in Hep2 laryngocarcinoma via the IL-6/JAK-STAT (signal transducer and activator of transcription) axis leading to tumor progression." (PMID 41159021, 2025). "We investigated whether anti-MIF therapy could enhance the antitumor effects of the immune checkpoint inhibitor anti–programmed cell death 1 (anti–PD-1) in 2 murine tumor models." (PMID 41122966, 2025). "MIF plays a pivotal role in inflammatory signaling and tumor growth." (PMID 41159021, 2025). "Furthermore, high levels of MIF have been associated with transcriptional down-regulation of NKG2D on the NK cells, hence impeding its cytotoxic activity against the tumor cells." (PMID 41159021, 2025). "These interactions allow MIF to influence inflammation, immune response, and tumor progression." (PMID 41294749, 2025). "Strikingly, the inducible depletion of MIF significantly reduced tumor growth." (PMID 40835826, 2025). "Our recent studies in the constitutive MIF knock-out CRC mouse model revealed that MIF supports CRC development via tumor-associated macrophage recruitment and angiogenesis without affecting overall inflammation." (PMID 40835826, 2025). "According to some studies, MIF may also be a useful biomarker for laryngopharyngeal cancers, providing information on the existence and course of the tumor." (PMID 41159021, 2025). "Similarly, NPC2 positive macrophages secrete MIF acting on T cells, inhibiting T cell activity and mediating tumor immune escape." (PMID 40620715, 2025). "Furthermore, MIF promotes tumorigenesis by preventing ferroptosis in macrophages and driving them toward an M2-like phenotype, further supporting tumor progression." (PMID 41181127, 2025). "Moreover, some investigations regarding the role of MIF laryngopharyngeal tumor progression have been conducted." (PMID 41159021, 2025). "Indeed, tumor areas of TAM-treated tumors with a sufficient MIF ablation showed a strong reduction compared to oil-treated controls." (PMID 40835826, 2025). "Therapeutically, MIF represents a promising target for enhancing anti-tumor immunity." (PMID 41159021, 2025). "Furthermore, MIF’s role varies significantly across tumor types, stages, and even subclones within the same tumor." (PMID 41159021, 2025). "Inhibition of MIF secreted by tumor cells after radiotherapy could promote M1 polarization of microglia and produce an inhibitory effect on tumor growth." (PMID 38685050, 2024).